CCL2 (C-C motif chemokine ligand 2)
Diseases named in the same sentence as CCL2 in open-access papers (continued):
Sharing a sentence is not in itself a finding about the gene and the disease.
tumor (continued). "CCL2 consistently exerts a dual role in the tumor microenvironment." (PMID 29312296, 2017). "Numerous cell types influence macrophage function including the tumor cells themselves, which not only recruit macrophages to both primary and metastatic tumor sites by secreting chemokines such as CCL2, CCL5 and CXCL12, but also differentiate and polarize them to a tumor-promoting phenotype." (PMID 28881599, 2017). "Furthermore, three-dimensional reconstructed confocal images of dissected mouse lungs (common site of metastasis in this model) showed significantly fewer tumor cells and macrophages after treatment with anti-CCL2 antibody." (PMID 28382036, 2017). "These monocytic MDSCs migrate to tumor microenvironment mainly by CCL2 and CSF-1 signaling and may differentiate locally into TAMs." (PMID 28197019, 2017). "Taken together, our findings suggest that CCL2 may have a more pro-tumor effect on tumor growth than an anti-tumor effect." (PMID 28143493, 2017). "Because 3LL cells failed to secrete cytokines in response to CD95L in vitro, we conclude that endogenous TRAIL/TRAIL-R induces secretion of CCL2 from tumor cells in a FADD-dependent manner and that this CCL2 is required to facilitate the accumulation of tumor-promoting myeloid cells in vivo." (PMID 28212753, 2017). "Because TRAIL/TRAIL-R-induced CCL2 elicited its tumor-supportive effect via CCR2, we also determined whether, and if so, which, immune cell markers and cytokines were co-regulated with composite TRAIL/CCR2 expression." (PMID 28212753, 2017). "Moreover, CCL2 stimulates monocytes to migrate to the tumor, and there they are converted in MDSC and immunosuppressive tumor-associated macrophages and facilitate the tumor growth." (PMID 28499389, 2017). "TAM may either originate from resident macrophages or are attracted from the bone marrow and spleen to the tumor site by the CCL2 (also known as monocyte chemoattractant protein-1 (MCP-1))." (PMID 28471401, 2017). "Chemokines such as CCL2, CCL5, CCL7, CCL8, CXCL12 and growth factors, for example, M-CSF, PDGF, and VEGF aggressively recruit blood monocytes at the tumor site, where they distinguish in tumor-associated macrophages." (PMID 29450136, 2017). "Since the effects of CCL2 on TEN appeared to be limited to less aggressive tumor cells, we examined whether differences in CCL2 secretion may influence the response to exogenous CCL2 to enhance tumor cell killing." (PMID 28143493, 2017). "Tumor-associated macrophages (TAMs) play a role in tumor angiogenesis and are recruited into the tumor microenvironment (TME) by secreted chemokines, including Monocyte Chemoattractant Protein-1 (MCP-1/CCL2)." (PMID 28475599, 2017). "CCL2 is involved in the recruitment of monocytes to the tumor site." (PMID 28471401, 2017). "This tumor invasion-dependent decrease of CCL2 at estropause might represent a long-term effect of P4 on infiltration of tumor-associated macrophages (TAMs) during peritoneal tumor spread in this model." (PMID 28966800, 2017). "Disrupting this axis by targeting CCR2 or CCL2 has resulted in reduced mobilization of inflammatory monocytes from the bone marrow and peripheral blood to tumour sites, which correlated with increased survival and decreased tumour burden in mouse models of lung metastasis and pancreatic cancer." (PMID 28210073, 2017). "Furthermore, exclusively in co-culture with ADSCs, the different BRCAs were exposed to several important tumor-modulating proteins, such as CCL2, HGF, or interleukins." (PMID 28545495, 2017). "The targets of aptamers actually in clinical trials are extracellular proteins (VEGF165, C5, PDGFβ, coagulation factor IXa, A1 domain of von Willebrand factor, thrombin, TFPI, CXCL12, CCL2, hepcidin peptide hormone), except nucleolin which is highly expressed at the surface of several tumor cells." (PMID 28635657, 2017).
tumor (continued). "Macrophages flocked to the tumour, the so-called tumour-associated macrophages (TAMs), are generally recruited by the activation of CSF1R by CSF-1 or IL-34, as well as by the chemokine CCL2." (PMID 28404796, 2017). "Indeed, pharmacological inhibition, neutralising monoclonal antibodies, or genetic mutation of chemoattractants such as CCL2, VEGFR2, CSF-1R depleted TAM infiltration and reduced tumour growth." (PMID 29065107, 2017). "Moreover, the decreased tumor burden in mice injected with shTRAIL-R cells significantly correlated with decreased CCL2 protein and transcript levels in shTRAIL-R cell-containing lungs." (PMID 28212753, 2017). "Blockade of either CCL2 or CCR2 has shown pre-clinical anti-tumor success." (PMID 28467800, 2017). "Macrophages can be recruited to tumour sites by tumour-derived CCL2 that binds to CCR2." (PMID 28210073, 2017). "Thus, exogenous CCL2 favors 67NR tumor colonization in vivo, even though it can enhance 67NR tumor cell killing by TEN in vitro." (PMID 28143493, 2017). "Western bolt analysis supports that blockade of B7‐H3 could effectively attenuate the recruitment of MDSCs and M2 macrophages by reducing chemokine CXCL1 and CCL2 in the tumour." (PMID 28401653, 2017). "To evaluate the idea that higher tissue levels of CCL2 might make changes in the microenvironment that can inhibit tumor growth, we delivered increasing amounts of CCL2 intranasally to mice and monitored the concentration of CCL2 in the lung." (PMID 28143493, 2017). "Our data obtained in mice, together with these human data, suggest that a TRAIL/CCL2 axis might also be involved in modulating the human tumor immune microenvironment." (PMID 28212753, 2017). "CCL2 may play a protective role by mediating early immune surveillance in the tumor progression process through a process that involves recruitment of γ,δ tumor infiltrating lymphocytes (TILS) to the tumor microenvironment." (PMID 28143493, 2017). "TGFβ is known to suppress CCL2 expression, thus it is expected that TGFβR2KO PyMT cells will express more CCL2 and thus provide a good model for exploring the role of CCL2 production by tumor cells in metastasis." (PMID 28143493, 2017). "We confirmed that CCL2 expression was increased in tumor tissues derived from WT8/CCL2 cells." (PMID 27666332, 2016). "Importantly, several myeloid cell chemoattractants are increased across different tumor tissues including the predominate ligand for CCR2+ IM: CCL2." (PMID 27852031, 2016). "IL-1β and TNF-α may alter stromal cells enhancing the expression of CCL2, CXCL8, and CCL5 by cancer-associated fibroblast and mesenchymal stem cells in the inflammatory tumor microenvironment of breast cancer." (PMID 27886105, 2016). "Importantly, systemic delivery of anti-VEGFA/CCL2 or pre-miR-1, pre-miR-206 and anti-miR-31 significantly inhibited tumor angiogenesis, TAMs accumulation, tumor growth and lung metastasis." (PMID 27541266, 2016). "And In mice, CCL2/CCL2 axis blockade lessened inflammatory monocytes and macrophages from the primary tumor site and pre-metastatic liver, leading to enhanced antitumor immunity, regressed tumor growth, and delayed metastasis." (PMID 27409666, 2016). "Analysis of the tumor tissues revealed that radiation up-regulates both CCL2 and CCL5." (PMID 27014915, 2016). "Notably, we have previously reported CDDO-Me-mediated down-regulation of CCL2 expression in PyMT tumor cells." (PMID 26918785, 2016). "We found that IL-1β induced CCL2 expression in macrophages and tumor cells." (PMID 27786298, 2016). "Using a WT8 subclone in which CCL2 was overexpressed and a 786‐O subclone in which CCL2 expression was knocked down, we found that CCL2 overexpression enhanced and CCL2 knockdown suppressed tumor growth, angiogenesis, and macrophage infiltration in vivo." (PMID 27666332, 2016).
tumor (continued). "In summary, our study has identified and proven that infiltrated mast cells could enhance BCa metastasis via stimulating the ERβ/CCL2/CCR2/EMT/MMP9 signaling pathway in the BCa tumor microenvironment." (PMID 26556868, 2016). "More recently study revealed that, mesenchymal stem-like cells(MSLCs), the progenitor cells of fibroblast and adipocyte, which could migrate to tumor sites and then promote tumor growth, were also recruited by CCL2/CCR2 pathway." (PMID 26992207, 2016). "IL-17A could stimulate ESCC tumor cells to produce much more chemokines, such as CCL2, CCL20 and CXCL13." (PMID 26942702, 2016). "For the first time, our study proves that the tumor microenvironment mast cells could stimulate the ERβ/CCL2 signals, and consequently leads to an increased BCa cell invasion." (PMID 26556868, 2016). "The mRNA expression of CCL2 was twice as high as that in the control tumor cells." (PMID 27888616, 2016). "MSC-derived CCL2/MCP-1 attracts macrophages to tumors and thereby promotes tumor growth." (PMID 27388156, 2016). "In addition, tumor cells can recruit TAMs, the major inflammatory components of the tumor microenvironment by secreting the colony stimulating factor (CSF-1), the chemokine ligands 2, 3, 4, 5, and 8 (CCL2, 3, 4, 5, and 8) and VEGF." (PMID 27044404, 2016). "Examples of key players of cancer-related inflammation (CRI) include tumor-infiltrating lymphocytes, tumour-associated macrophages (TAMs), the secretion of cytokines such as TNF, IL-1, IL-6, and chemokines such as CCL2 and CXCL8, in addition to the occurrence of tissue remodeling and angiogenesis." (PMID 27555866, 2016). "We confirmed that CCL2 expression was decreased in tumor tissues derived from 786‐O/shCCL2 cells." (PMID 27666332, 2016). "Overexpression of CCL2 by tumor cells can lead to their destruction by an infiltrate of activated mononuclear cells and may indicate a more favorable prognosis." (PMID 27191744, 2016). "As demonstrated in several malignancies including CRC, overexpression of CSF1 and CCL2 may result in accelerated tumor progression and poor prognosis." (PMID 26799669, 2016). "Through an indirect mechanism, the reduction in macrophages in CCL2 deficient tumors may have also affected CSC renewal, as M2 macrophages express soluble factors that promote cancer stem cell renewal, tumor growth and invasion." (PMID 27283985, 2016). "However, further molecular and animal experiments are needed to test that inflammasome/IL-1β-induced CCL2 regulates the recruitment of macrophages in tumor microenvironments and metastatic sites." (PMID 27786298, 2016). "Furthermore, we provide evidence that dl922-947-induced reduction of IL-8 and CCL2 production correlates with impaired tumor angiogenesis and decreased macrophage density in vitro and in vivo." (PMID 26625205, 2016). "Despite this, it is clear that a reduction in plasma CCL2 associated with EPA treatment is linked to a marked difference in tumor biology evidenced by the differential gene expression between tumors from patients who did or did not exhibit a ‘CCL2 response’." (PMID 27058904, 2016). "However, further studies are required to prove that inflammasome pathways modulate tumor microenvironments through CCL2-mediated recruitment of myeloid cells from the bone marrow." (PMID 27786298, 2016). "One of the mechanisms of CCL2 in tumor progression is through its involvement in angiogenesis." (PMID 27666332, 2016). "Several reports have demonstrated that CCL2 plays an important role in tumor progression." (PMID 27666332, 2016). "Our results show that IL-1β induced the expression of CCL2 in macrophages and tumor cells." (PMID 27786298, 2016). "At present, it is still unclear whether tumor progression with abundant TAMs could be enhanced or these TAMs could be polarized to M2 phenotype mainly by CCL2 overexpression in ccRCC." (PMID 27666332, 2016).
tumor (continued). "However, tumor cells from neu+, neu+Ccl2-/-, and neu+Ccr2-/- mice grow at similar rates in culture, and adding neutralizing CCL2 antibodies to wild type tumor cells or exogenous CCL2 to Ccl2-/- tumor cells did not affect their proliferation." (PMID 27820834, 2016). "In contrast, antibody neutralization of CCL2 in tumor xenografts enhanced tumor cell apoptosis." (PMID 27283985, 2016). "The effects of inhibiting serpinE2 in tumors are multifaceted: ERK signaling was lowered, CCL2 levels were decreased, a skewing of tumor-promoting M2-like macrophages towards the M1-like phenotype was observed, and the level of the protease inhibitor TIMP1 increased." (PMID 27793045, 2016). "LTβR signalling is well known to recruit lymphoid and myeloid cells into lymphoid organs and tumours, and activation mediates accumulation of macrophages and NKT/T cells in association with increased expression of CXCL10 and CCL2 in AKT/CAT and AKT/NICD tumours." (PMID 26206664, 2016). "Interestingly, CCL2 overexpression induces tumor angiogenesis via TAMs, and VEGFA production in regions of hypoxia in growing tumors benefits TAM accumulation." (PMID 27541266, 2016). "We determined the effects of CCL2 gene silencing on primary tumor growth and invasion." (PMID 27283985, 2016). "Indeed, this study showed that depletion of macrophages from RCC xenografts overexpressing CCL2 by administration of clodronate liposomes also suppressed tumor growth and angiogenesis." (PMID 27666332, 2016). "Similarly, we identified CCL2/CCR2 axis as a tumor promoter in NPC metastasis through upregulating MMP2/9 via ERK1/2 pathways." (PMID 26701209, 2016). "Since targeting T/E fusion alone cannot stop tumor growth completely, in combination of other NF-kB inhibitor and/or blocking CCL2 pathway may be an efficacious approach for this major group of PCas carrying T/E fusion." (PMID 25749044, 2015). "Tumor-promoting macrophages are recruited from blood to tumor sites by CCL2 and CCL5." (PMID 25909600, 2015). "In conclusion, the present study provided a novel insight into how CCL2 affected tumor progression." (PMID 25695619, 2015). "It is hypothesized that by attracting macrophages into the microenvironment and inducing these cells to release a series of factors, CCL2 promotes tumor cell generation and angiogenesis, and increases the chance of metastasis." (PMID 25695619, 2015). "CAFs secrete monocyte chemotactic protein 1 (MCP1/CCL2) and stromal-cell-derived factor 1 (SDF1), also known as CXCL12, which are involved in the recruitment of myeloid-derived suppressor cells (MDSCs) and tumor-associated macrophages (TAMs)." (PMID 28536400, 2015). "Furthermore, analysis of serum samples from MC38 tumour bearing mice also revealed a notable reduction in CCL2 levels, whereas serum levels of CXCL10 and CXCL1 were unaffected." (PMID 26358505, 2015). "Moreover, tumor derived factors such as PTHrP (parathyroid hormone-related protein) and CCL2 induce direct and indirect changes in the bone and tumor microenvironment that contributed to tumor growth." (PMID 26459393, 2015). "The majority of studies into CCL2 signalling describe its tumorigenic features, but CCL2 is also known to provide protection, for example, by recruiting anti-tumorigenic T cell subsets to the tumour microenvironment." (PMID 25990313, 2015). "Tumor production of certain chemokines, especially the chemokine CCL2, is a major driver of monocyte mobilization of inflammatory (CCR2+) monocytes from the bone marrow and recruitment into tissues, where the monocytes mature into tumor macrophages, which support the growth of tumor metastases." (PMID 29061951, 2015). "We therefore propose that tumor cells secrete TNF, which induces CCL2 production in two microenvironment cells (myofibroblasts and macrophages) promoting tumor migration, invasion and extravasation and monocyte recruitment and differentiation into tumor associated macrophages." (PMID 26327448, 2015).
tumor (continued). "Studies have successfully shown that targeting CCL2 signaling using neutralizing antibody to CCL2 can significantly inhibit PCa tumor growth and migration in vivo including both VCaP (the only endogenously T/E fusion expressing PCa cell line) subcutaneous and intratibial injection models." (PMID 25749044, 2015). "These analyses revealed that the tumours are characterized by expression of inflammatory chemokines (CCL2, CCL5, CCL7, CCL8, CCL12, CXCL9, CXCL10 and CX3CL1), reflected by an enrichment of activated Foxp3− and Foxp3+ T cells expressing T helper type 1-associated chemokine receptors." (PMID 25495686, 2015). "These trends are in line with the observed CCL2 mRNA expression and protein secretion; however, this does not preclude an effect by other chemokines that may be produced by tumor-conditioned macrophages." (PMID 26177198, 2015). "Interestingly, enhanced LPS-induced CCL2 production by 4T1-conditioned macrophages was evident up to 72 h of tumor-conditioning." (PMID 26177198, 2015). "However, due to CCL2 (monocyte chemoattractant protein 1, MCP1) produced by cancer cells and tumor stromal cells, namely TAMs and CAFs, T-cells that infiltrate tumors become immunosuppressive CD4+ CD25+ T regulatory leucocytes (Tregs)." (PMID 25695337, 2015). "While the secretion of these cytokines from the primary tumor undoubtedly plays a role in metastatic progression, our observations strongly suggest that priming of distal macrophages can result in secondary production of TNFα, IL-6, and CCL2." (PMID 26177198, 2015). "Peritoneal lavages and lysates of recovered tumor were monitored for CCL2, CCL9 and CCL5 levels." (PMID 26647964, 2015). "Specifically, in bone, CCL2 is known to be involved in a destructive cascade, being released after PTHrP stimulation of osteoblasts, which in turn secretes CCL2 in the bone marrow activating osteoclastogenesis and tumor growth." (PMID 26459393, 2015). "CCL2 secreted by tumor cells can recruit monocytes and TAMs." (PMID 26294325, 2015). "The therapeutics of possible underlying mechanisms are the improvement of the tumor microenvironment through the suppression of NF-κB and subsequent cytokines such as TGF-β, IL-10, VEGF, COX-2, CCL2 and CCL22, and enhancement the function of transferred CD8+ T-cells." (PMID 26683520, 2015). "MSCs isolated from spontaneous lymphomas have a strikingly high expression of CCL2 compared with bone marrow-derived MSCs (BM-MSCs), and promote tumor growth by recruiting type 2 like TAMs to tumor site, a phenomenon that can be mimicked by treating BM-MSCs with tumor necrosis factor alpha (TNF-α)." (PMID 25857315, 2015). "However, humanized monoclonal CCL2 neutralizing antibody (CNTO888) is ineffective in suppressing serum CCL2 level or tumor progression due to feedback mechanism that increases CCL2 production." (PMID 26275794, 2015). "We therefore hypothesized that decreased secretion of CCL2, and possibly other factors, by shCoREST1 cells could contribute to reduced angiogenesis through modulation of macrophages in the shCoREST1 tumor microenvironment." (PMID 25793264, 2015). "Because Ccl2 and Ccl20 are critical inflammatory mediators, their expressions were also determined by real-time PCR and Western blot methods on day 28 to investigate additional mechanisms involved in the anti-tumor immunity of IL-17." (PMID 26684834, 2015). "Many tumor derived factors are known to promote osteoclastogenesis such as PTHrP and CCL2." (PMID 26459393, 2015). "In addition, CCL2 has been shown to be critical for cell proliferation of CNS tumors, cancer cell metastasis, as well as tumor aggressiveness." (PMID 26528477, 2015). "Similar to the effects seen in BMDMs, peritoneal macrophages from 4T1 tumor-bearing mice exhibited significantly strengthened production of IL-6 and moderately increased production of CCL2 and TNFα in response to LPS when compared to macrophages from control mice." (PMID 26177198, 2015).